LINC01007 (long independently transcribed non-coding RNA 1007)
Gene: Long non-coding RNA gene on chromosome 7 (101,561,719 to 101,569,018, reverse strand). Ensembl gene ENSG00000233123.
Diseases named in the same sentence as LINC01007 in open-access papers:
LINC01007 is named in the same sentence as 1 disease in open-access papers, as found by Europe PMC text mining. Sharing a sentence is not in itself a finding about the gene and the disease. The quoted sentences say what the papers report.
glioma (1 paper, 2021). A benign or malignant brain and spinal cord tumor that arises from glial cells (astrocytes, oligodendrocytes, ependymal cells). "In glioma grade III, highly activated DEGs included CFAP45, PLBD1, RASSF9, IGKV3-11, IGKV1-5, and NTS, while highly downregulated DEGs included NPAS4 and LINC01007." (PMID 33948562, 2021).